WT1 (WT1 transcription factor)
Diseases named in the same sentence as WT1 in open-access papers (continued):
Sharing a sentence is not in itself a finding about the gene and the disease.
uterine cancer (3 papers, 2020 to 2023). Primary or metastatic malignant neoplasm involving the uterine corpus and/or the cervix. "The objective of the current meta-analysis was to investigate the diagnostic and prognostic role of WT1 expression in patients with uterine carcinoma." (PMID 32859123, 2020). "The Wilms tumour 1 (WT1) marker is being considered a targeted treatment in cancer immunotherapy, particularly for its potential role in the immunoreactivity of uterine cancers." (PMID 37296736, 2023). "In fact, considering the possibility of WT1 expression also in uterine cancers, difficulty in assigning tumor origin can persist in a minority of cases." (PMID 32859123, 2020). "In detail, a total of 35 studies with 1616 patients assessed the role of WT1 expression in patients with uterine carcinoma." (PMID 32859123, 2020). "The overall rate of WT1 expression in uterine carcinoma was 25%." (PMID 32859123, 2020). "Studies were considered eligible if they evaluated the WT1 expression in uterine carcinoma." (PMID 32859123, 2020). "Moreover, our study suggests that WT1 may be a potential marker to predict the prognosis of patients with uterine cancer, but more studies are needed to confirm its role in clinical practice." (PMID 32859123, 2020).
adenofibroma (2 papers, 2023 to 2025). A benign neoplasm characterized by the presence of connective tissue stroma and epithelial structures. "While pleomorphic adenoma and metanephric adenofibroma can be differentiated based on a history of prior salivary gland tumor, metanephric adenofibroma is associated with strong nuclear immunoreactivity for WT1 and BRAF V600E in the epithelial component." (PMID 41268216, 2025). "Metanephric adenofibroma are tumors of mixed epithelial and mesenchymal origin and the epithelial component expresses WT-1, whereas the invaginated tubules in MST are negative for WT-1." (PMID 37454137, 2023).
Adrenal insufficiency (2 papers, 2012 to 2016). Insufficient production of steroid hormones (primarily cortisol) by the adrenal glands. "In addition to defects in testis differentiation, we found that double heterozygous Wt1+/−; Sf1+/− fetuses lacked adrenal glands and that neonates die shortly after birth, presumably from adrenal insufficiency." (PMID 22496664, 2012).
anaplastic astrocytoma (2 papers, 2018 to 2020). "The least frequently positive histopathologic types were grade II diffuse astrocytoma (81.8%), then pilocytic and anaplastic astrocytomas (85.7% each) and most of these tumor types were of WT1 score+1 (54.5, 50 and 71.4% in the same order)." (PMID 32856872, 2020). "While grade II diffuse astrocytoma was the least frequently positive type and most of diffuse and anaplastic astrocytomas exhibited a focal pattern +1 WT1 score." (PMID 32856872, 2020).
aplastic anemia (2 papers, 2022 to 2024). Anemia resulting from bone marrow failure (aplastic or hypoplastic bone marrow). "Quantitative assessment of Wilm’s tumor-1 (WT1) mRNA has emerged as a valuable tool for gauging MDS disease status and distinguishing it from related disorders, such as aplastic anemia." (PMID 39087180, 2024).
asthma (2 papers, 2022). "Interestingly, asthma-related TFs, including WT1, ZEB1, and RERE, were negatively associated with most of hub genes." (PMID 35169275, 2022). "We found PDCD11 was negatively associated with asthma-related TFs, including WT1, ZEB1, and RERE; ALDH18A1 was negatively associated with WT1 and RERE; SEC61A1 was negatively related with WT1 and ZEB1." (PMID 35169275, 2022). "Furthermore, in conditions such as asthma and chronic obstructive pulmonary disease, WT1 was reported to act as a repressor of MMP-9." (PMID 35243014, 2022). "The network analysis revealed that transcription factor (TF) WT1, ZEB1, RERE, FOSL1, and miR-20a may be involved in the development of asthma." (PMID 35169275, 2022).
cardiac hypertrophy (2 papers, 2024 to 2025). "Conversely, combined knockout of WT1 in endothelial and myeloid-derived cells increases infarct size, cardiac hypertrophy, fibrosis, hypoxia, and lymphocyte infiltration." (PMID 40585983, 2025). "In light of the pivotal function of WT1 in cardiac development, one of our early studies examined its possible role in cardiac hypertrophy." (PMID 39768169, 2024). "In animals with WT1 knockout in endothelial and hematopoietic-derived cells, already in the acute phase after MI, heart-to body weight ratios were increased and cardiomyocyte diameters determined by measurements of HES and WGA-stained sections higher indicating cardiac hypertrophy." (PMID 40585983, 2025). "Thus, WT1 re-expression does not appear to be related to cardiac hypertrophy but to cardiac ischemia." (PMID 39768169, 2024).
chronic heart failure (2 papers, 2020 to 2023). "Interestingly, the benefit of LCZ696 treatment which reduces significantly the mortality of patients with chronic heart failure seems also to be associated with increased heart vascularisation, as a result of increased endothelial and WT1+ cell proliferation." (PMID 33245046, 2020).
clear cell ovarian tumors (2 papers, 2019 to 2021). "The positivity for ER and negativity for WT1 is also suggestive of a close relationship with endometrioid and clear cell ovarian tumors." (PMID 33736662, 2021).
cutaneous melanoma (2 papers, 2020 to 2021). A primary melanoma arising from atypical melanocytes in the skin. "WT1 somatic mutations are described in several cancers, with cutaneous melanoma having the greatest prevalence." (PMID 32850962, 2020). "In summary, frequency of WT1 mutations and CNVs in our skin melanomas dataset are 3.7 and 1.3%, respectively." (PMID 32850962, 2020). "Two similarly sized WES analysis of 100 and 114 skin melanomas found WT1 somatic mutations in the 3 and 1.8% of skin melanoma patients, respectively." (PMID 32850962, 2020). "Importantly, in Wilms (WT1) tumor cells, uveal and cutaneous melanoma cells as well as in normal podocytes and retinal pigmental epithelial cells, SRPIN340 or SPHINX31 has been previously shown to increase the expression of the anti-angiogenic VEGF165b splice variant." (PMID 34433435, 2021).
cystic kidney (2 papers, 2025). "Further study on the mechanisms linking WT1 variants and renal cyst formation is warranted." (PMID 41450889, 2025). "The data collectively suggest that the WT1 zinc finger variant could show the cystic kidney appearance when other cystogenic modifiers coexist." (PMID 41450889, 2025).
diaphragmatic hernia (2 papers, 2015 to 2021). A congenital or acquired weakness or opening in the diaphragm which allows abdominal contents to protrude into the chest cavity; congenital diaphragmatic hernias are caused when the embryonic diaphragm fails to fuse. "An elegant study showed that conditional deletion of Wt1 using a G2-Gata4-Cre results in the mice developing diaphragmatic hernias." (PMID 33735101, 2021). "Homozygous Wt1 null mouse embryos die at ∼E13.5 and have diaphragmatic hernias." (PMID 33735101, 2021). "We show that the conditional deletion of Wt1 in the non-muscle mesenchyme using Prx1-Cre results in diaphragmatic hernias, and we illustrate that the mesenchymal cells of the PPFs are capable of expanding towards the PHMP." (PMID 33735101, 2021). "They appear abnormally formed and variably reduced in number in fetuses with abnormal mesothelial Wilms Tumor 1 (WT1) function, diaphragmatic hernia and in ectopic liver nodules without mesothelium." (PMID 26265759, 2015).
endometrial serous adenocarcinoma (2 papers, 2012 to 2015). A high grade, aggressive adenocarcinoma arising from the endometrium. "WT1 is an immunohistochemical biomarker used for distinguishing ovarian versus endometrial serous adenocarcinomas." (PMID 22371431, 2012).
endometrioid tumor (2 papers, 2017 to 2023). A benign, borderline, or malignant epithelial tumor of the female reproductive system characterized by the presence of glands and/or cysts lined by neoplastic cells that resemble endometrial cells. "For example, WT1 is a marker of serous tumors, and ARID1A is somatically mutated in ∼50% of clear cell and ∼30% of endometrioid tumors." (PMID 29312534, 2017). "The authors also looked at the expression of WT-1, which is supposed to be predominantly positive among serous tumors but mostly negative among endometrioid tumors." (PMID 36968229, 2023).
ependymoma (2 papers, 2018). A WHO grade II, slow growing tumor of children and young adults, usually located intraventricularly. "Increased incidence of high WT1 expression levels have been observed to correlate with severity of tumor grade of pediatric ependymoma with highest levels present in grade III anaplastic ependymoma." (PMID 29623275, 2018).
epithelial ovarian tumors (2 papers, 2006 to 2021). "There are many reports showing that in epithelial ovarian tumors, serous tumors generally revealed a high WT1 gene expression." (PMID 16606472, 2006). "In epithelial ovarian tumors, WT1 expression has been detected." (PMID 16606472, 2006).
esophageal squamous cell carcinoma (2 papers, 2024 to 2025). Esophageal squamous cell carcinoma (ESCC) is a type of esophageal carcinoma (EC) that can affect any part of the esophagus, but is usually located in the upper or middle third. "Cancer cells expose cancer antigens on their surface, such as CA125 (MUC16) (cancer antigen 125), HE4 (human epididymis protein 4), WT1 (Wilms’ tumor 1), NY-ESO-1 (New York esophageal squamous cell carcinoma 1), or mesothelin, which T lymphocytes can recognize." (PMID 40362280, 2025).
fibrosis (2 papers, 2023). the formation of excess fibrous connective tissue in an organ or tissue in a reparative or reactive process. "However, changes in the methylation level of the “driver” genes for oncopathology (АРС, CDKN2B, GSTP1, ELF4, TERT, WT1) are registered in tumor tissue in the setting of liver cirrhosis but not fibrosis." (PMID 36923478, 2023).
gonadal agenesis (2 papers, 2013 to 2017). A congenital disorder characterized by the complete absence of gonadal tissue. "It has been reported that abortion of WT1 leads to gonadal agenesis owing to the failure of genital ridge development." (PMID 28152522, 2017). "It has been reported that Wt1 is essential for GR development and deletion of Wt1 results in gonadal agenesis due to the failure of GR development." (PMID 23497137, 2013).
graft versus host disease (2 papers, 2020 to 2023). An immune system disorder that occurs after allogeneic hematopoietic stem cell transplant and is a reaction of donor immune cells against host tissues. "Results from two WT1 TCR Phase I/II trials utilizing autologous T cells are expected to clarify the relationship, if any, between graft versus host disease (GvHD), which has been seen in trials, and WT1-targeting (NCT02550535, NCT01621724, NCT02408016)." (PMID 33569049, 2020).
granulosa cell tumor (2 papers, 2016 to 2023). A slow-growing, malignant tumor, characterize by the presence of granulosa-like cells and Call-Exner bodies, that is almost always found in the ovary. "In our patient, negativity of WT-1 ruled out granulosa cell tumors, and negative CK7 and CK99 ruled out a neuroectodermal origin." (PMID 27729065, 2016).
Hepatic steatosis (2 papers, 2022). Steatosis is a term used to denote lipid accumulation within hepatocytes. "We suggest that browning of epididymal WAT depots contributes to reduced diet-related hepatic steatosis and increased whole-body glucose tolerance in mice with a single intact Wt1 allele." (PMID 34846543, 2022). "Compared with their wild-type littermates, Wt1 mutant mice exhibit significantly improved whole-body glucose tolerance and much weaker hepatic steatosis when kept on a high-fat diet for 11 weeks." (PMID 35372335, 2022). "Compared to their wild-type littermates, Wt1 heterozygous mice exhibit significantly improved whole-body glucose tolerance and alleviated hepatic steatosis under high-fat diet." (PMID 35372335, 2022). "Strikingly, mice with a heterozygous Wt1 gene show improved whole-body glucose tolerance and alleviated diet-induced fatty liver disease." (PMID 34846543, 2022).
Hypercalcemia (2 papers, 2013 to 2024). An abnormally increased calcium concentration in the blood. "Herein, we describe a case of BCR-ABL positive ALL with a triploid karyotype, WT1, and CDKN2A mutations with hypercalcemia and bone destruction as the first manifestations." (PMID 38450181, 2024). "When xenografted into immunodeficient mice, BIN-67 cells developed into tumours that reflected the hypercalcemia and histology of human SCCOHT, notably intense expression of WT-1 and vimentin, and lack of expression of inhibin." (PMID 23433318, 2013).
intrahepatic cholangiocarcinoma (2 papers, 2016 to 2024). A carcinoma that arises from the intrahepatic bile duct epithelium in any site of the intrahepatic biliary tree. "The present study identified cytoplasmic WT1 as a novel marker for intrahepatic cholangiocarcinoma." (PMID 27829047, 2016).
ischemia (2 papers, 2021 to 2024). A hypoperfusion of the BLOOD through an organ or tissue caused by a PATHOLOGIC CONSTRICTION or obstruction of its BLOOD VESSELS, or an absence of BLOOD CIRCULATION. "As we identified c-Kit as a transcriptional target of Wt1 in the context of vascular formation, it seems conceivable that mobilization of c-Kit precursor cells represents one mechanism of Wt1-mediated cardiac neovascularization after ischemia." (PMID 34299295, 2021). "In summary, based on the essential expression of WT1 in the embryonic heart and its reactivation after damage, it should be considered as one of the genetic targets that could induce regenerative responses in cardiomyocytes after ischemia." (PMID 39768169, 2024).
liver cancer (2 papers, 2021 to 2022). An epithelial or non-epithelial malignant neoplasm that arises from the liver. "Studies have shown that SJC can inhibit the expression of the WT1 oncogene in liver cancer cells through the Wnt/β-catenin signaling pathway." (PMID 36120378, 2022). "In liver cancer cells, WT1 can affect the expression of IGFBP1, which may affect the progression and cell survival." (PMID 34692659, 2021).
liver cirrhosis (2 papers, 2016 to 2023). "Improvement of liver function was associated with upregulation of the hepatocyte differentiating factor HNF4α and downregulation of Wilms' tumor 1 (WT-1), a nuclear factor upregulated in liver cirrhosis which has been shown to mediate hepatocellular dedifferentiation." (PMID 27658043, 2016).
liver disease (2 papers, 2019 to 2025). "Given the relationship between mesenchyme and WT1, we examine WT1 expression by HSCs in fibrotic liver disease." (PMID 31615982, 2019). "While mesothelial-mesenchymal transition has been suggested to account for the emergence of Wt1-positive HSC in disease, we demonstrate that a Wt1-positive HSC population (cHSC) exists already during homeostasis and is a likely source of fibrogenic cells in liver disease." (PMID 40954217, 2025).
malignant peripheral nerve sheath tumor (2 papers, 2014). Malignant peripheral nerve sheath tumor (MPNST) is a rare and often aggressive soft tissue sarcoma occurring in a wide range of anatomical sites. "WT1 expression has been variably reported in both benign and malignant peripheral nerve sheath tumors (MPNSTs) by means of immunohistochemistry." (PMID 25474318, 2014).
malignant peritoneal mesothelioma (2 papers, 2021 to 2025). An aggressive malignant mesothelioma that arises from the peritoneum. "Immunohistochemistry, including markers such as calretinin, WT1, and BAP1, plays a pivotal role in confirming the diagnosis and differentiating malignant peritoneal mesothelioma from metastatic adenocarcinoma." (PMID 41147025, 2025).
malignant rhabdoid tumor of the kidney (2 papers, 2021 to 2024). "As a control, cDNA of a WT1-expressing malignant rhabdoid tumor of the kidney (MRTK) model was taken along, which, indeed, showed expression of all regions of the WT1 gene." (PMID 34885181, 2021).
metastatic carcinoma (2 papers, 2018 to 2020). A carcinoma which has spread from the original site of growth to another anatomic site. "Immunohistochemical markers are essential to the diagnosis, with an initial mesothelial cell panel which may include calretinin, CK 5/6, WT-1 and D2-40 being used to differentiate mesothelial cell origin from metastatic carcinomas." (PMID 33014860, 2020).
mucinous tumors (2 papers, 2021 to 2022). "The negativity for CK20, CDX2, and WT1 and positivity for ER and PR is useful in routine practice in differentiating borderline seromucinous tumors from borderline serous and mucinous tumors." (PMID 33736662, 2021). "Borderline mucinous tumors are characterized by their non-Mullerian differentiation with the absence of WT1, estrogen and expression of progesterone receptors." (PMID 35909430, 2022).
Myelodysplasia (2 papers, 2018 to 2023). Clonal hematopoietic stem cell disorders characterized by dysplasia (ineffective production) in one or more hematopoietic cell lineages, leading to anemia and cytopenia. "Finally, a recent study demonstrated that a subset of aged Wt1-haploinsufficient mice developed features of myeloproliferation and myelodysplasia, including hepatomegaly with CD45+/Mac1+/Gr1+ infiltration, and megakaryocyte dysplasia in the bone marrow." (PMID 30450160, 2018).
nephrotic syndrome, type 4 (2 papers, 2020). Nephrotic syndrome within the first three motnhs of life, characterized initially by increased mesangial matrix, with or without hypertrophy and hyperplasia of podocytes, and eventual glomerular sclerosis. "Trio ultra-rapid whole-genome sequencing identified a novel, likely pathogenic, de novo missense variant (c.485T > A, p.Val162Asp) in WT1 in 46 h, consistent with a diagnosis of nephrotic syndrome type 4 (NPHS4; OMIM 256370)." (PMID 32843431, 2020).
ovarian carcinosarcoma (2 papers, 2022 to 2023). A highly aggressive malignant neoplasm arising from the ovary.
ovarian small cell carcinoma (2 papers, 2020 to 2023). A carcinoma that arises from the ovary and is characterized by the presence of small malignant cells. "COV434 cells, which were commonly considered as granulosa-like cells but recently reclassified as small cell ovarian carcinoma, did not express most granulosa markers, but did express high levels of WT1 and NR2F2." (PMID 36803359, 2023).
papillary renal cell carcinoma (2 papers, 2013 to 2023). A rare subtype of renal cell carcinoma, arising from the renal tubular epithelium and showing a papillary growth pattern, which typically manifests with hematuria, flank pain, palpable abdominal mass or nonspecific symptoms, such as fatigue, weight loss or fever. "Immunohistochemically, the tumor cells were positive for WT-1 and CD57 but negative for AMACR, which was helpful to exclude the possibility of papillary renal cell carcinoma." (PMID 24083046, 2013).
parathyroid tumors (2 papers, 2016 to 2023). "An additional technical advantage of utilizing WT1 IHC staining in parathyroid tumors is that WT1 IHC staining is readily available in most pathology laboratories without difficulties in performance and interpretation." (PMID 37121965, 2023). "We have demonstrated that the expression level of WT1 is significantly decreased in MEN1-parathyroid tumors compared to normal parathyroid tissues." (PMID 26871472, 2016). "In addition, several studies have demonstrated that the expression levels of WT1 were reduced in parathyroid tumors." (PMID 26871472, 2016).
pediatric cancer (2 papers, 2019 to 2024). "The analysis detected mutations in several cancer-related genes previously reported to be implicated in pediatric cancer, such as CTNNB1, WT1, AMER1, and NF1." (PMID 38672648, 2024).